INS (insulin)
Diseases named in the same sentence as INS in open-access papers (continued):
Sharing a sentence is not in itself a finding about the gene and the disease.
Insulin resistance (continued). "As regard mean values of fasting glucose, insulin and HOMA index of insulin resistance, they showed higher significant values in group II (p=0.0001)." (PMID 31244307, 2019). "Energy restriction consistently reduced liver fat content in a linear fashion, but induced pronounced and opposite alterations in fasting insulin and FGF-21 already after 3 days, suggesting rapid improvement of insulin resistance." (PMID 31685793, 2019). "However, deficits in insulin signaling beyond the IR could contribute to insulin resistance." (PMID 31849810, 2019). "In the leptin- and insulin-related pathways, PTP1B and SOCS3 are negative regulators and make major contributions to leptin and insulin resistance." (PMID 31344867, 2019). "Conversely, LIN28 with muscle-specific deletion increases insulin resistance, indicating that LIN28 has an important role in modulating insulin sensitivity." (PMID 30641913, 2019). "Obese pre-DM patients showed high values of glucose, insulin resistance (HOMA-IR), C reactive protein (CRP), nitrotyrosine, tumor necrosis factor-α (TNF-α) and interleukin 6 (IL-6), and low values of insulin (p < 0.05)." (PMID 30845774, 2019). "Studies have shown that obesity-induced ERS results in insulin resistance and T2DM, mainly through activation of the JNK terminal, a mediator that leads to an alteration in insulin signaling." (PMID 31551782, 2019). "Previous reports show that this polymorphism is associated with fasting insulin, the homeostatic model assessment of insulin resistance (HOMA-IR), and insulin secretion in Chinese T2D subjects." (PMID 30764545, 2019). "The presence of GDM due to impaired insulin secretion, apart from GDM due to elevated insulin resistance during pregnancy, has been recently reported." (PMID 31275653, 2019). "Third, to show an antidiabetic effect in an animal model of extreme insulin resistance, we conducted an oral dosing study in aged (27-week-old) ZDF rats that were completely resistant to insulin." (PMID 31092829, 2019). "HFD for 15 weeks significantly reduced the levels of insulin-stimulated phospho-AKT in liver tissues, suggesting that HFD would induce hepatic insulin resistance." (PMID 31780766, 2019). "The increase in those surrogate markers of insulin resistance were primarily driven by hyperinsulinemia in the ERaKOs in response to HFD; ERaKOs fed HFD exhibited a fourfold increase in fasting insulin compared to NC (G×D, P = 0.036)." (PMID 30804793, 2019). "HIT also reduced insulin resistance (HOMA-IR), mainly due to a reduction in circulating insulin levels." (PMID 31632301, 2019). "They foundthat co-supplementation, led to decreased serum insulin levels(p=0.03), homeostasis model of assessment of the insulin-resistance(HOMA-IR) score (p=0.04), and a significant rise in thequantitative insulin-sensitivity check index (QUICKI) (p=0.001)." (PMID 31091067, 2019). "Insulin resistance can induce CRC and CAPs through the growth-promoting effects of elevated insulin, glucose, or triglycerides." (PMID 31142015, 2019). "Insulin resistance may mediate GDM and HDP with intrauterine programming of epigenome, because insulin resistance was putative as pathogenesis of HDP and GDM in pregnant women, and cord plasma insulin level was positively associated with birth weight and neonatal fat mass." (PMID 31616376, 2019). "ITT assay showed a higher response to injected insulin, and HOMA-IR showed a decrease in insulin resistance in GDF11 treated mice." (PMID 31847906, 2019). "It is particularly important to provide early diagnostics in people with metabolic disturbances, especially including fasting insulin and HOMA-IR, which are necessary to reveal insulin resistance." (PMID 31428627, 2019). "After surgery, insulin resistance (HOMA2-IR C-peptide) decreased in parallel in NGT and T2D subject and remained ~50% reduced at the late follow-up, but T2D patients were more insulin resistant than NGT subjects at all times." (PMID 31641146, 2019).
Insulin resistance (continued). "Changes in fasting blood glucose and insulin levels induced by HFGFD, indicating insulin resistance in these animals, were further reflected in a significant increase in the HOMA-IR index." (PMID 31882668, 2019). "The homeostasis model assessment of insulin resistance (HOMA-IR) and insulin levels were also reduced." (PMID 31167512, 2019). "The morbidly obese groups presented significantly higher levels of insulin, free fatty acids (FFA), triglycerides, leptin, adiponectin, and homeostasis model assessment of insulin resistance (HOMA-IR) results (p < 0.05)." (PMID 30813326, 2019). "In a prospective, controlled study of insulin resistance in GD 1 patients, baseline glucose parameters were comparable in GD1 subjects and controls and, after 3 years of ERT, the subjects were more insulin resistant vs. controls." (PMID 31791361, 2019). "In contrast to HC subjects, the T2DM patients were markedly insulin resistant (high HOMA-IR index) and had markedly increased fasting plasma glucose, hemoglobin A1C, insulin, and triglyceride levels." (PMID 31600210, 2019). "We determined the hepatic insulin resistance status by OGTT, ITT and western blot analysis of hepatic insulin signaling components." (PMID 31215394, 2019). "It has been revealed that adipocyte hypertrophy shows the positive correlation with insulin resistance (measured by HOMA-IR) and fasting plasma insulin in humans." (PMID 31827683, 2019). "Quantitative insulin sensitivity check index (QUICKI) and homeostasis model assessment-insulin resistance (HOMA-IR) were also calculated." (PMID 30871514, 2019). "Increasing insulin secretion (represented by increasing C-peptide levels) in response to an antidiabetic treatment might indicate two mechanisms: stronger compensation of growing insulin resistance or restoration of initially impaired insulin secretion capacity." (PMID 31717901, 2019). "Jiangtang Xiaozhi administration resulted in a significantly reduced serum insulin level and HOMA-IR index score, indicating reduced insulin resistance." (PMID 31881654, 2019). "The glucose tolerance test and insulin tolerance test clearly demonstrated that 12-week HFD feeding induced glucose intolerance and insulin resistance." (PMID 31262297, 2019). "We also measured plasma insulin and glucagon levels and then calculated HOMA-IR to determine the effect of LGZG on insulin resistance." (PMID 31396097, 2019). "Several studies have demonstrated a tendency toward insulin resistance (IR) in children and adolescents with CAH, as assessed by increased plasma insulin concentrations and HOMA-IR." (PMID 31031703, 2019). "This was most likely due to increased insulin resistance in HFS mice and decreased circulating insulin levels in HFS + CUR mice compared to HFS mice." (PMID 31372175, 2019). "Female adolescents with high BF% (G2 and G3) had higher NC, WC, WHtR, and percentages of gynoid and android fat, as well as higher insulin resistance index (HOMA-IR), insulin, and leptin concentrations." (PMID 31933541, 2019). "The identification of molecular mechanisms by which glucose and insulin regulate SGLT1 have set this transporter, and its potential role in the physiopathology of hyperglycemia and intestinal insulin resistance, in the spotlight." (PMID 31905727, 2019). "In addition to inducing insulin resistance, RBP4 may also have impact on insulin secretion from beta-cells, as genetic studies have shown that SNP risk alleles rs3758539 (A) and rs34571439 (G) in the RBP4 gene were associated with reduced insulin secretion." (PMID 30651745, 2019). "Evaluation was performed in many studies, using techniques like calculation of the homeostatic model assessment for insulin resistance (i.e., HOMA-IR), insulin tolerance testing and euglycemic insulin (i.e., glucose clamp) infusion." (PMID 31849810, 2019).
Insulin resistance (continued). "Nevertheless, the lipid changes observed in the subjects in this pilot study reflect an insulin-sensitizing effect, insofar as the TG : HDL ratio, which is considered a surrogate for insulin resistance, was significantly reduced." (PMID 31485454, 2019). "However, MCD diet associated weight loss improves insulin sensitivity demonstrating that the nearly 2.5 fold hepatic increase of this ceramide species may not suffice to cause insulin resistance." (PMID 31521175, 2019). "It is noteworthy to mention that GITR engagement demonstrated not only a preventive role against the onset of insulin resistance but also therapeutic effects, as the binding of the GITR specific agonist on ILC2s improved insulin sensitivity of diabetic mice." (PMID 30755607, 2019). "Our results show that insulin resistance, as measured by HOMA-IR, and related insulin and lipid disturbances are more common amongst South Asians than Europeans." (PMID 31063476, 2019). "Collectively, these studies indicate that insulin signaling likely plays important roles in regulating both LEC metabolism and lymphangiogenesis; LEC insulin resistance diminishes lymphatic function, and exacerbates obesity and metabolic abnormality." (PMID 31798464, 2019). "Adiponectin can act as an insulin sensitizer, while pro-inflammatory cytokines, such as TNF-α and IL-6, contribute to insulin resistance." (PMID 31731774, 2019). "The fasting serum insulin was measured, and HOMA-IR (homeostatic model assessment of insulin resistance) was calculated." (PMID 31013777, 2019). "In senescent HAECs, insulin signaling is impaired and increased levels of GM1 contribute to insulin resistance." (PMID 31013778, 2019). "When challenged with a HFD, adipose-Piezo1−/− mice showed exacerbated insulin resistance as evidenced by significantly increased glucose levels in GTT and ITT, and elevated insulin and HOMA-IR index." (PMID 31263454, 2019). "Next, the homeostasis model assessment of insulin resistance (HOMA-IR) and quantitative insulin sensitivity check index (QUICKI) values were compared among the groups (for the calculations)." (PMID 30841887, 2019). "SMRT mRID1 mice were also resistant to the glucose lowering effects of insulin-sensitizing drugs such as TZDs and AICAR, indicating that the RID1 is needed to protect the mice from diet-induced insulin resistance." (PMID 31293521, 2019). "Upon a high-fat diet, insulin and glucose levels increase over time in C57BL/6J males, consistent with insulin resistance and glucose intolerance, whereas C57BL/6J females have normal serum insulin concentrations and glucose levels remain constant." (PMID 30949516, 2019). "Visfatin reduced the levels of insulin-signaling proteins, including p-IR, p-IRS-1 (Tyr612), p-AKT, and p-GSK-3α/β, triggering insulin resistance." (PMID 31396538, 2019). "This in turn would lead to less available insulin and IGF1 receptor expression, with insulin resistance resulting." (PMID 31849810, 2019). "In obesity and insulin resistance conditions, PNPLA3 expression is induced by insulin and hepatocytes and hepatic stellate cells, and localizes at the surface of lipid droplets." (PMID 31375010, 2019). "Chronic hyperinsulinemia resulting from insulin resistance has been shown to decrease insulin-INSR complex internalization and lead to derangements of intracellular receptor trafficking and insulin degradation." (PMID 31658625, 2019). "Given that insulin-sensitizers are the most reliable form of improving metabolic profiles in PCOS patients, they may be the best line of treatment for PCOS patients with insulin resistance, especially if combined with some other weight loss strategy in obese patients." (PMID 31367382, 2019). "As an intracellular energy sensor, AMPK is another well-known suppressor of gluconeogenesis in addition to insulin pathway and the suppression of AMPK accompanies insulin resistance." (PMID 31861309, 2019).
Insulin resistance (continued). "As there are not any clinically accepted definitions for insulin resistance, we choose to use two different classifications of insulin resistance, high HOMA-IR >3.8 and top quartile of insulin concentration." (PMID 31230225, 2019). "The significance of GPR55 as a potential regulator of insulin action and energy homeostasis is further strengthened by the finding that GPR55−/− mice exhibit insulin resistance and increased adiposity." (PMID 30148676, 2019). "Although there is an inadequate understanding of the etiology of PCOS, insulin resistance is a relatively common feature of the disease and the pathophysiology of PCOS involves alterations in insulin action in a variety of target tissues." (PMID 31681178, 2019). "In particular, TNF-α, IL-6, and IL-1β interfere with insulin signaling through the activation of MAPK and nuclear factor kappa-light-chain-enhancer of activated B cells (NFkB), resulting in insulin resistance." (PMID 30621146, 2019). "Second, we detected insulin signaling by examining the expression of p-AKT and AKT in adipose tissues, which are the most critical tissue in the initiation and development of insulin resistance." (PMID 31426846, 2019). "Surrogate parameters for insulin resistance (HOMA-IR) and insulin secretion (HOMA-β%) confirmed a mild insulin resistance (IR) in alb-SREBP-1c and a strong IR in obob mice." (PMID 31137678, 2019). "This study showed the beneficial effect of soy in elderly women with borderline parameters of MetS who suffered from a hyperlipidemic, insulin resistance status (TG/HDL-C > 3.5, HOMA-IR > 2.5 and fasting insulin > 12.5) and oxidative stress (MDA ≥ 5)." (PMID 31249633, 2019). "The secondary outcomes include the fasting blood glucose (FBG), fasting insulin (FINS), homeostasis model assessment of insulin resistance (HOMA-IR), and quantitative insulin sensitivity check index (QUICKI)." (PMID 31277146, 2019). "With evidence supporting the effect of SFA on alleviating insulin resistance in HepG2 cells, we sought to determine the effect of SFA on insulin sensitivity, metabolic parameters and ceramide biosynthesis in a mouse model of obesity and insulin resistance." (PMID 31137828, 2019). "Fasting morning insulin was reduced by 47% in the LFWL group and 25% (marginally significant) in the LFWM; however, HOMA-IR (homeostatic model assessment for insulin resistance) reduction was significant in both groups." (PMID 31207908, 2019). "In mature differentiated 3T3-L1 adipocytes naringenin treatment prevented the insulin-induced glucose uptake, reduced tyrosine phosphorylation of IRS-1 and reduced adiponectin levels, indicating induction of insulin resistance." (PMID 30871083, 2019). "A meta-analysis assessed the effects of vitamin K supplementation on a homeostasis model assessment of insulin resistance (HOMA-IR), fasting plasma glucose and insulin, CRP, adiponectin, leptin, or IL-6 levels." (PMID 30857216, 2019). "Compared with OS, the patients in the OR group had significantly increased body weight, fasting blood glucose and insulin levels, and the HOMA-IR significantly increased, which indicated an insulin resistance status." (PMID 30733507, 2019). "In particular, insulin resistance and hyperinsulinemia play a critical role in the development of HCC because insulin can exert a potentially mitogenic effect by activating its receptor in both precancerous and cancer cells." (PMID 30704150, 2019). "Insulin resistance, a clinical feature of PCOS, is a decreased ability of insulin to mediate metabolic actions on glucose uptake, production, and/or lipolysis." (PMID 31507635, 2019). "AC-YVAD-CMK treatment markedly decreased caspase-1 activity, serum IL-1β, blood glucose, fasting serum insulin levels, and HOMA, an indicator of insulin resistance." (PMID 31387986, 2019). "Blood glucose and fasting insulin levels were markedly elevated in HFD-fed mice and showed a higher HOMA insulin resistance index." (PMID 31616013, 2019).
Insulin resistance (continued). "The list her includes Homeostasis Model Assessment for Insulin Resistance (HOMAIR), HOMA2 index, glucose insulin ratio (GI ratio), Quantitative Insulin Sensitivity Check Index (QUICKI), Fasting Insulin Resistance Index (FIRI)." (PMID 31223343, 2019). "Insulin resistance was developed in HFD-fed mice, as demonstrated by a reduced response to insulin load (D presenting absolute and relative values of blood glucose, respectively)." (PMID 31847157, 2019). "CLE also decreased plasma C-peptide, a marker of insulin secretion, and both CLE and LU supplements significantly lowered the HOMA-IR index, indicating an improvement of insulin resistance." (PMID 31208033, 2019). "Peripheral insulin resistance (PIR) and central brain insulin resistance (BIR) and impaired insulin signaling seem to be the link between T2DM and LOAD." (PMID 31569571, 2019). "FGF23 knockout mice presented with reduced fat mass, developed hypoglycemia and increased peripheral insulin sensitivity, and showed improved subcutaneous glucose tolerance, suggesting a link between FGF23 and insulin resistance." (PMID 31736870, 2019). "Taken together, these data demonstrate that normalized insulin-signaling pathway by both EWH and IRW is a contributing factor to the improved glucose uptake in TNF-α-induced insulin resistance." (PMID 29955954, 2019). "A primary feature of insulin resistance in LS is reduced GLUT-4 insulin-mediated glucose uptake in muscle and adipose tissue." (PMID 31133852, 2019). "In accordance with the whole-body insulin resistance, it was observed that all the disease animal models, except the HF+STZ model, exhibited increased fasting insulin values." (PMID 31141900, 2019). "Furthermore, Stevioside improved insulin resistance induced by food, and delayed the induction of insulin resistance in the high-fructose chow fed animals together with a reported ability of increasing the insulin response, and thereby insulin sensitivity, in STZ-diabetic rats." (PMID 31438580, 2019). "Most studies have examined the use of one of two classes of insulin‐sensitizing drugs on NASH: thiazolidinediones (pioglitazone and rosiglitazone) or biguanides (metformin), for improving insulin resistance as a possible treatment for NASH." (PMID 31782258, 2019). "Insulin secretion (HOMA-beta) improved significantly in 44–56% of patients, whereas insulin resistance was significantly aggravated (HOMA-R: 1.30–1.78)." (PMID 31905944, 2019). "After 4 weeks, resveratrol improved insulin resistance and increased the phosphorylation of protein kinase B (AKT), which plays a key role in insulin signaling by interfering directly with glycogen synthesis." (PMID 31597344, 2019). "The evidence of the linkage between SUA and insulin resistance in type 2 diabetes is growing, but it is unclear if SUA within the normal range directly lead to declines in insulin sensitivity in T2DM patients." (PMID 30941277, 2019). "Insulin resistance was regulated by KMOS via the AMPK pathway, the insulin signaling pathway, and the downstream pathways of the mTOR and glycogen metabolic pathways in HG-induced insulin-resistant HepG2 cells." (PMID 31344867, 2019). "Epidemiological and clinical evidence indicates that SCH is positively correlated with insulin levels, HOMA-IR (Homeostasis Model Assessment-Insulin Resistance) values and diabetes." (PMID 31156553, 2019). "Because of the ability of pioglitazone to interfere with ET-1 system as well as to increase peripheral insulin sensitivity, this compound might be a promising therapeutic option in patients with resistant hypertension and in those with hypertension concomitant with insulin resistance." (PMID 31712626, 2019). "Despite no change in adiposity, 10 day olanzapine treatment was associated with an increased homeostatic model assessment of insulin resistance (HOMA-IR) and also with decreased insulin sensitivity." (PMID 31555747, 2019).